CD8A (CD8 subunit alpha)
Diseases named in the same sentence as CD8A in open-access papers (continued):
Sharing a sentence is not in itself a finding about the gene and the disease.
myeloma (213 papers, 2008 to 2026). "Interestingly, mature CD11c+CD8a+XCR1+CD11b- cDC1s accumulated in the bone marrow 14 and 24 days after myeloma transplantation." (PMID 39474418, 2024).
metastatic tumors (211 papers, 2006 to 2026). "We found that the highest difference in correlation coefficient between primary and metastatic tumors was the association between CYT level and the CD8A expression." (PMID 33476333, 2021). "Increased expression of IFN-γ was observed in benign lesions compared to the malignant and metastatic tumors, whereas a slight decrease in CD8α expression was observed in metastatic tumors, albeit without statistical significance." (PMID 32225066, 2020). "The decrease in CD8A+ NKT cells, known for their potent anti-tumor activity, in metastatic tumors highlights a potential mechanism by which HGSOC evades immune-mediated destruction." (PMID 38975339, 2024). "The expression of CD8A was increased in primary tumors with neoantigens in RYR3 and DNAH7 and in recurrent/metastatic tumors with neoantigens in TTN and PIK3CA." (PMID 33796222, 2021).
parasitemia (208 papers, 2007 to 2025). "CD8α-/- mice were extremely susceptible to T. cruzi infection and displayed uncontrolled parasitemia at day 21, even with an infection dose of 100 trypomastigotes, which was 50 times less than the dose used in previous experiments." (PMID 30364284, 2018). "Depletion of CD8+ T cells with antibodies to CD8α or CD8β increased parasitemia in PyNL infection, with ~50% mortality." (PMID 31608052, 2019). "In wild-type mice, the initial recognition of T. gondii by TLR11 and TLR12 expressed by CD8α+ cDCs triggers early IL-12 production and NK cell-mediated secretion of IFN-γ leading to control parasite infection." (PMID 32669460, 2020).
atherosclerosis (207 papers, 2010 to 2026). A disease characterized by the build-up of fatty material and calcium deposition in the arterial wall resulting in partial or complete occlusion of the arterial lumen. "Therefore, upon CLEC9A deletion, the increased expression of IL10/IL-10 in the BM and CD8α+ DCs seem to be the main cause of reduced recruitment or the activation of macrophages in plaque sites, as well as the alleviation of atherosclerosis." (PMID 39528464, 2024). "However, complete knockout of the CD8 gene in atherosclerosis-susceptible ApoE−/− mice, presumably affecting both CD8α+ DC and CD8+ Tcell function, did not lead to the expected reduction in atherosclerosis." (PMID 26486587, 2015). "In Apoe−/− mice, Batf3 deletion (Batf3−/−) attenuated CD8α+ DCs, thereby reducing the localization of macrophages to aortic plaques, resulting in the suppression of inflammation and the prevention of atherosclerosis." (PMID 39528464, 2024). "CD8α+ dendritic cells aggravate atherosclerosis, likely by inducing Th1 cell response, which promotes CCL5 expression in macrophages and increased infiltration of leukocytes and lesion inflammation." (PMID 34122426, 2021). "In this study we aimed to clarify the exact contribution of Batf3-dependent cells in atherosclerosis that comprise both CD8α+ as well as CD103+ APC subsets." (PMID 28771609, 2017). "Addressing the function of single effector molecules expressed by CD8α/CD103+ APC- will help to further dissect their contribution to atherosclerosis." (PMID 28771609, 2017). "In summary, we did not identify other DC or DC-like populations likely to have taken over cross-presentation from the depleted CD8α+ DCs in this atherosclerosis model." (PMID 26486587, 2015). "Collectively, CD8α+ DCs play atherogenic roles by inducing the chemotactic recruitment of macrophages to the plaque, resulting in the escalation of inflammation and the progression of atherosclerosis." (PMID 39528464, 2024). "In agreement with a previous report showing that loss of CD8a+ DCs did not affect atherosclerosis in mice, immunization did not alter CD8a+ DCs in our study." (PMID 29091929, 2017). "Moreover, atherosclerosis in ApoE−/− mice is also unaffected by genetic disruption of CD8a." (PMID 31653058, 2019). "Here, both routes of cross-presentation were ablated by depleting CD8α+ DC and CD103+ DC in a well-established mouse model of atherosclerosis." (PMID 26486587, 2015). "Interestingly, this pathway seems to have different roles in different DC subtypes, as deletion of Atg16l1 in CD8α+ DCs did not affect the development of atherosclerosis compared to CD11b+ DCs." (PMID 38397127, 2024). "However, as severe CD8α+ DC depletion did not increase plaque burden, a cross-tolerogenic role for CD8α+ DCs in atherosclerosis seems unlikely." (PMID 26486587, 2015).
rheumatoid arthritis (197 papers, 1996 to 2026). A chronic, systemic autoimmune disorder characterized by inflammation in the synovial membranes and articular surfaces. "CD8a is a potential prognostic and diagnostic marker for inflammatory disorders and tumors, used to predict severity in chronic rhinosinusitis and as a biomarker for rheumatoid arthritis." (PMID 39075660, 2024). "This KO line identifies a model that will permit in depth interrogation of the pathogenesis of rheumatoid arthritis, including the role of CD8α+ DCs and other cells of the immune system." (PMID 25963626, 2015).
triple-negative breast carcinoma (180 papers, 2012 to 2026). An invasive breast carcinoma which is negative for expression of estrogen receptor (ER), progesterone receptor (PR), and human epidermal growth factor receptor 2 (HER2). "Elevated CD8A gene expression and increased infiltration of CTLs in triple-negative breast cancer (TNBC) contribute to enhanced antitumor immunity and improved prognosis." (PMID 39199375, 2024). "We calculated the overall survival of non-metastatic, triple-negative breast cancer patients included in the METABRIC according to the ratio between the expression of CD8A and FOXP3 genes (CD8A/FOXP3 ratio)." (PMID 34362334, 2021).
renal cell carcinoma (165 papers, 2000 to 2026). "In the renal cell carcinoma case, “small nests” of tumors showed a higher density of CD8A, CD8B, and CD4 expression than “large nests,” and these transcript levels were even higher in regions of desmoplasia surrounding vessels." (PMID 35584630, 2022).
HCMV infection (156 papers, 2006 to 2026). "A study of chronic cytomegalovirus infection in macaques demonstrated that the antigen-specific T cell population was highly enriched within the CD4+CD8α+ DP T cells relative to CD4+ SP T cells." (PMID 39912921, 2025). "Treml6 gene expression is induced by type I IFN produced in response to mouse cytomegalovirus infection in CD8α+ and CD11b+ conventional dendritic cells (cDCs)." (PMID 27141827, 2016).
myocarditis (153 papers, 2009 to 2025). Myocarditis is a condition that is characterized by inflammation of the heart muscle (myocardium). "It has been shown that the expansion of CD8α+ DCs confers protection during myocarditis caused by CVB332." (PMID 31611578, 2019).
osteosarcoma (151 papers, 2005 to 2026). A usually aggressive malignant bone-forming mesenchymal neoplasm, predominantly affecting adolescents and young adults. "present a high-resolution single-cell atlas of MTAP-deleted osteosarcoma, revealing deficiency in CD8A+ T cells." (PMID 39983717, 2025). "Guo said that in osteosarcoma disease, the high CD8a expression group has a better survival probability than the low CD8a expression group, which belongs to the protective gene." (PMID 36482887, 2022). "Methionine restriction or MAT2A inhibitor SCR6639 increases CD8A+ T cell infiltration in the tumor microenvironment, enhancing the efficacy of immune checkpoint therapy in MTAP-deleted osteosarcoma." (PMID 39983717, 2025). "We conferred that the high expression of PLOD2 in osteosarcoma may repress immune cell infiltration, especially CD4 and CD8A T cells." (PMID 36276118, 2022).
Stroke (144 papers, 2012 to 2025). Sudden impairment of blood flow to a part of the brain due to occlusion or rupture of an artery to the brain. "Three days after stroke, administration of anti-CD8α mAb led to reduced brain infarct size in perioperative stroke mice (P < 0.0001) and stroke-only mice (P = 0.0262) compared with isotype IgG-treated mice." (PMID 35799259, 2022). "Of these, the cytotoxic lymphocyte marker Cd8a was kept at high levels in aged rats at day 14 post-stroke." (PMID 23251410, 2012). "Moreover, compared with isotype IgG-treated mice, administration of anti-CD8α mAb lead to reduced Tunel+ cells (P < 0.0001) and increased NeuN+ cells (P < 0.0001) in the ischemic penumbra with perioperative stroke mice." (PMID 35799259, 2022).
head and neck cancer (142 papers, 2002 to 2026). A primary or metastatic malignant neoplasm affecting the head and neck. "For example, in head & neck cancer (HNSC), PD-L1 expression is significantly associated with poor outcome only after adjusting for CD8A expression (HR = 1.20[95%CI: 1.02-1.41], p < 0.03)." (PMID 31523194, 2019). "We evaluated RNA-seq data from TCGA and found K17 expression level was inversely correlated with that for CD8A and CXCL9 in a cohort of 513 patients with head and neck cancer." (PMID 31968015, 2020).
Granuloma (136 papers, 2007 to 2025). A compact, organized collection of mature mononuclear phagocytes, which may be but is not necessarily accompanied by accessory features such as necrosis. "Instead, the proportion of CD8α− γδ T cells in granulomas increased and had similar function as CD8α+ γδ T cells, thereby replacing production of IFN-γ, TNF, IL-2, and/or IL-17." (PMID 39912921, 2025). "By 8 wk after infection, granulomas increased in all animals in the unvaccinated group and in a subset of animals in the CD4- and CD8α-depleted groups." (PMID 39912921, 2025). "The number of cells in granulomas did not change following CD4 or CD8β depletion but significantly increased following depletion of all CD8α+ lymphocytes." (PMID 39912921, 2025). "Still, the CD4-depleted group (median: 4.5) and CD8α-depleted group (median: 3) had significantly higher numbers of granulomas than the nondepleted vaccinated controls (median: 0), and a small number of clearly unprotected animals in each group had extensive disease (e.g., TB pneumonia)." (PMID 39912921, 2025).
dengue (126 papers, 2006 to 2026). "Taken together, our results show that antigen targeting to CD8α+ DCs using DNA vaccines is a promising strategy to induce cellular and humoral responses and may be used in the development of more efficient dengue vaccines." (PMID 30761131, 2019). "A similar effect may explain previous claims of CD8α on monocytes subsequent to dengue virus infection." (PMID 17678538, 2007).
sarcoma (124 papers, 2010 to 2025). A usually aggressive malignant neoplasm of the soft tissue or bone. "Analysis of the TCGA confirmed significant differences in survival among human sarcoma patients with high and low expression of genes associated with greater immune activation and cytotoxicity (CD3e, CD8a, IFN-γ, perforin, and CD122/IL-2 receptor beta)." (PMID 32084139, 2020). "The correlations between the expression of ST2 and CD4, CD8A, and CD33, and between IL-33 and CD8A and CD45RO were then validated by analysis using GSE2719 or GSE 967 GEO datasets of sarcoma." (PMID 29896199, 2018). "The correlations between the expression of IFN-γ and CD3E, CD8A, and CD45RO were then validated by analysis using GSE2719 or GSE967 datasets of sarcoma." (PMID 29896199, 2018). "Given the strong correlation between PDCD1 and CD8A in the TCGA sarcoma cohort, the next analysis addressed whether PD1+ cells harbored a similar prognostic potential as CD8+ cells in combination with CD11c+ cells." (PMID 33803245, 2021). "Correlation analyses using sarcoma data of TCGA showed that the expression of IFN-γ was positively correlated with that of CD4 and CD45RO, but strong positive correlations were observed with CD3E and CD8A expression." (PMID 29896199, 2018).
latent infection (122 papers, 2004 to 2026). "Thus, we propose that infection of CD8α+ DCs by HSV-1 reduces the antiviral response, resulting in greater latency, which in turn leads to increased recruitment of CD8 T cells at the site of latent infection." (PMID 24695322, 2014).
pancreatic ductal adenocarcinoma (117 papers, 2013 to 2026). An infiltrating adenocarcinoma that arises from the epithelial cells of the pancreas. "Extending the analysis to other cancer types, we discovered that MBNL1 expression also had a high positive correlation with CD8A expression for several other cancer types, including Testicular Germ Cell Tumors (TCGT) and Pancreatic Ductal Adenocarcinoma (PAAD)." (PMID 40305509, 2025).
squamous cell carcinoma (117 papers, 2003 to 2026). A carcinoma arising from squamous epithelial cells. "Oral and squamous cell carcinoma samples were divided into four combinations based on the median value of gene expression levels for nine pairs of genes (CD8A-CD274, CD8A-CTLA4, CD8A-ICOS, CD8A-TNFRSF4, CD8A-CD27, CD8A-BTLA, CD8A-ADORA2A, CD8A-CD40LG, and CD8A-CD28)." (PMID 35127742, 2021).
acute myeloid leukemia (116 papers, 2013 to 2026). Acute myeloid leukemia (AML) is a group of neoplasms arising from precursor cells committed to the myeloid cell-line differentiation. "Additionally, it was found that the inhibitory receptor NKG2A is a dominant checkpoint for the ML NK-cell phenotype, and that CD8α+ donor NK cells correlate to treatment failure against AML acute myeloid leukemia (AML)." (PMID 37205105, 2023). "However, prior work by Fehniger and colleagues using cytokine-induced memory-like NK cells demonstrated that high levels of CD8α on donor memory-like NK cells correlated with treatment failure in patients with relapsed/refractory acute myeloid leukemia (AML) after adoptive transfer." (PMID 39087476, 2024).
esophageal cancer (109 papers, 2010 to 2026). A primary or metastatic malignant neoplasm involving the esophagus. "Furthermore, ENTPD1 expression in esophageal carcinoma tissues was positively correlated with the expression of genetic markers of multiple TIICs, including CD8A and CD8B of CD8+ T cells, with or without adjustment for tumor purity." (PMID 36831526, 2023).
ZIKV infection (109 papers, 2017 to 2026). "ZIKV infection of Cd8a−/− mice resulted in high mortality, demonstrating that T cells can protect against ZIKV infection." (PMID 38793562, 2024).
endometrial cancer (107 papers, 2007 to 2026). Primary or metastatic malignant neoplasm involving the endometrium (mucous membrane that lines the endometrial cavity). "As previously observed, LAG-3 is co-expressed with CD8A and PD-L1 in most tumor types, and overexpression is observed in endometrial cancer as well." (PMID 36077354, 2022). "However, it was observed that T cell exhaustion markers (LAG-3, TIM-3, TIGIT) and T cell inhibitors (PD-1, CTLA-4) were strongly correlated with CD8A expression in all endometrial cancers of all molecular subtypes." (PMID 36077354, 2022).
Listeria monocytogenes infection (106 papers, 2009 to 2025). "The loss of c-Jun and JunB in DC progenitors diminishes the CD8α cDC1 pool and thus confers resistance to Listeria monocytogenes infection." (PMID 33758366, 2021). "A study of Listeria monocytogenes infection revealed a direct role for CD8α+ DCs in promoting bacterial disease." (PMID 29867941, 2018). "Innate immunity to Listeria in mice depends on tissue-resident macrophages and CD8α+ dendritic cells responding to Listeria infection by secreting pro-inflammatory cytokines including TNFα, IL-12, and IL-6." (PMID 25599590, 2015). "Subsequent studies in the Listeria infection model have identified the CD8α+ DC subset as the cells responsible for efficient CD8 T-cell activation, as well as serving an important role in establishing a productive infection." (PMID 22862959, 2012). "Both the number of CD8α+ DC and the magnitude of CD8 T-cell expansion following Listeria infection in old mice could be partially restored by treatment with Flt3L treatment." (PMID 22862959, 2012).
liver fibrosis (105 papers, 2008 to 2025). "In comparison, mice in the anti-CD8α + PBS group showed comparable degrees of liver fibrosis to those in the anti-Iso + PBS group." (PMID 41214839, 2025).
pneumonia (104 papers, 2007 to 2026). An acute, acute and chronic, or chronic inflammation focally or diffusely affecting the lung parenchyma, caused by an infection in one or both of the lungs (by bacteria, viruses, fungi, or mycoplasma.). "The expression levels of CD8a, CD14, CD270 and CD 59 were increased, while CD16 and CTLA4 were decreased compared with patients with pneumonia." (PMID 34841705, 2021). "Of subsets of CD3+ T cells, the frequencies of cluster 06 identified as NKT cell with markers of CD3+ CD3+CD56+CD8a+TCRab+CD45RA+CCR7−CD45RO+Tbet+GranzymeB+ and cluster 12 as CD4+ TCM with markers of CD3+CD4+TCRab+CD45RA−CCR7+CD45RO+CD27+CD127+ significantly decreased in acute pneumonia." (PMID 34841705, 2021).
cerebral malaria (96 papers, 2008 to 2026). A sequestration of Plasmodium falciparum in the brain, which can cause coma and/or seizures. "In naïve mice and at the onset of cerebral malaria, CD8α+ dendritic cells (cDC1) are superior to other DC subsets for MHC II presentation of the ETRAMP epitope." (PMID 28935714, 2017).
cutaneous melanoma (94 papers, 2011 to 2026). A primary melanoma arising from atypical melanocytes in the skin. "Analysis of TCGA RNAseq data from cutaneous melanomas established that mRNAs encoding the CD8 T cell coreceptor subunits CD8α and CD8β have strong positive correlations with CD47 mRNA expression." (PMID 36768931, 2023). "Interestingly the behaviour of UM and cutaneous melanoma in the highest and lowest CD8A/PDL1 quart differs substantially." (PMID 31212986, 2019). "We next assessed the survival and expression of NK cell markers (NCR1 and NCR3) and CD8 T cell markers (CD8A and CD8B) in 448 patients with skin cutaneous melanoma reported in the TCGA database." (PMID 36458012, 2022). "However, when considering CD8A and PDL1 expression (a surrogate for tumour immunogenicity), almost 50% of cutaneous melanomas are considered CD8Ahigh/PDL1high, whereas the same percentage of UM are considered CD8Alow/PDL1low, reflecting a more immunosuppressed tumour microenvironment." (PMID 31212986, 2019).
Arthritis (93 papers, 2004 to 2026). Inflammation of a joint. "Interestingly, CD8α+ monocytes are often associated with rat models of disease involving immune-complex deposition and FcR-mediated pathology, such as arthritis, glomerulonephritis, ischaemia, and tumors." (PMID 17678538, 2007). "cDCs, particularly the CD8α+ subset, were reduced in the thymus, spleen and LNs before arthritis onset." (PMID 25963626, 2015). "Our results indicated that TSA treatment altered the CD8α+ conventional dendritic cell phenotype to that of the tolerogenic CD8α+ conventional dendritic cells and inhibited Th17 cell differentiation, leading to the suppression of arthritis in SKG mice, in which Th17 cells are critically involved." (PMID 21592365, 2011).